TNF (tumor necrosis factor)
Diseases named in the same sentence as TNF in open-access papers (continued):
Sharing a sentence is not in itself a finding about the gene and the disease.
cancer (continued). "The leading cause of FID in cancer is the release of pro-inflammatory cytokines associated with cancer, such as IL-6, IL-1, tumor necrosis factor α (TNF-α), and interferon-γ (IFN-γ)." (PMID 36567722, 2022). "Coincidentally, the risk of these three cancer types was shown to be significantly reduced for patients treated with TNF inhibitors in the secondary endpoint analysis of this study." (PMID 35945635, 2022). "Tumor proliferation and metastatic spread are promoted by neutrophils that are recruited by cancer-related chemokines and cytokines (e.g., IL-6 and TNF) which are highly present in advanced cancer patients and which are also associated with drug resistance." (PMID 35756636, 2022). "Among them, the PI3K-Akt signaling pathway, MAPK signaling pathway, IL-17 signaling pathway, TNF signaling pathway, cellular senescence, and proteoglycans in cancer were most closely associated with the mechanism of PD anticolon cancer." (PMID 36003525, 2022). "Tumor necrosis factor (TNF-α) is involved in all critical processes of cancer cachexia, including adipose tissue loss, skeletal muscle loss, changes in glucose, protein, and systemic inflammation." (PMID 35159388, 2022). "TNF-α is a key pro-inflammatory cytokine that is known to be associated with multiple inflammatory diseases, including cancer." (PMID 36361505, 2022). "As an angiogenic factor, TNF-α is released by many normal and cancer cells to regulate thriving or pathogenic angiogenesis once binding to its ligand on the cell membrane." (PMID 35955463, 2022). "This is the largest study to date evaluating the risk of newly diagnosed cancer following TNF inhibitor use in Korean patients with RA." (PMID 35945635, 2022). "For instance, GC cell-derived TNF-α triggers the IL-33 expression in cancer-associated fibroblasts through the TNFR2-NF-κB-IRF-1 axis." (PMID 35719369, 2022). "The incidence of cancer and cancer-related death was also associated with a high level of circulating IL-6, TNFα, and CRP in a five-year follow-up of elderly individuals." (PMID 36369012, 2022). "In general, cancer is a procoagulant state as it can activate the tissue factors and release inflammatory cytokines (i.e., TNF-α, IL-1β) which increases the risk of thrombosis and hence MI." (PMID 35228975, 2022). "This observational study aimed to investigate the association between IL-6, IL-8, and TNFα genetic single nucleotide polymorphisms (SNPs) and response to opioid therapy in a cohort of pediatric cancer patients." (PMID 35335997, 2022). "TNF-α and IL-6 are two key inflammatory cytokines linked to chronic inflammatory diseases and cancer." (PMID 36010601, 2022). "Sensitivity analysis based on various lag times of cancer development in the matched cohort demonstrated that the cancer risk tended to be consistently lower in the TNF inhibitor cohort." (PMID 35945635, 2022). "In contrast to TNFα, circulating levels of IL-6 were shown to correlate with weight loss in cancer patients and with reduced survival." (PMID 36078078, 2022). "TNF-α is associated with acute and chronic inflammation, autoimmune disease, and inflammation related to cancers." (PMID 36140220, 2022). "We previously reported that the cytokine TNF-α from the tumor microenvironment (TME) promoted tongue squamous cell carcinoma (TSCC) metastasis by activating cancer-associated fibroblasts (CAFs) and enhancing their release of SDF-1." (PMID 36291863, 2022). "The principal cause of FID in cancer is the release of pro-inflammatory cytokines such as IL-6, IL-1, TNF-α, and IFN-γ, which amplify hepcidin synthesis and thereby reduce the quantity of iron released into the circulation." (PMID 36143875, 2022). "MAPK14, hSP90AA1, and PTGS2 genes are associated with apoptotic biological processes, TNF signaling pathways, toll-like receptor signaling pathways, and cancer pathways." (PMID 36212968, 2022).
cancer (continued). "Treatment with TNF inhibitors was consistently associated with a lower risk of cancer than in the nbDMARD cohort (IR per 1000 person-years, 6.5 vs. 15.6; adjusted HR, 0.379; 95% CI, 0.255–0.563)." (PMID 35945635, 2022). "Recent studies reported that TNF-α secretion in cancer patients is associated with the signatures of specific microbiota." (PMID 36140470, 2022). "Targeted synthetic DMARDs, like JAK inhibitors, have shown efficacy in controlling RA activity although more recent data seem to suggest a higher risk of cancer and CV events compared to TNF inhibitors." (PMID 36352850, 2022). "The highly expressed TNF in macrophages in the S components was associated with upregulated DAG1 in cancer cells, which regulated cell growth and apoptosis." (PMID 35874770, 2022). "Under this background, the results of previous studies on the risk of cancer in patients with RA treated with TNF inhibitors are controversial." (PMID 35945635, 2022). "Further studies are needed on the role of CREB1 and TNF signaling in MSS cancers and their susceptibility to immunotherapy." (PMID 36387154, 2022). "Overexpression of the ACSL family in cancer is associated with TNFα‐mediated pro‐inflammatory activities, cancer progression, and poor prognosis." (PMID 36149760, 2022). "The study results indicated that the risk of cancer development was significantly lower in the TNF inhibitor cohort than the nbDMARD cohort before and after matching." (PMID 35945635, 2022). "In agreement with the previous studies, SZU251 + MUC1 caused a rapid induction of common cytokines such as IL6, TNFα and IFNγ in mouse BMDCs and spleen lymphocytes in vitro, favoring Th1-mediated immune responses and cytotoxic T cells acting on cancer cells." (PMID 36499455, 2022). "Because ALPK1 is associated with cancer development, the primary regulatory mechanism is activation of the NF-κB pathway through the inflammatory cytokine TNF-α." (PMID 36139553, 2022). "TNF is an inflammatory cytokine originally discovered for its capability to cause massive hemorrhagic necrosis of cancer lesions in mice." (PMID 35890309, 2022). "On the other hand, meta-analyses of randomized controlled trials demonstrated an increased or insignificant risk of cancer among patients receiving TNF inhibitors compared to those taking only nbDMARDs." (PMID 35945635, 2022). "This proinflammatory state also contributes to weight loss in patients with cancer, in which, as in HF, increased levels of tumor necrosis factor play a key role." (PMID 35160023, 2022). "Cancer induces inflammatory cytokines, such as interleukin (IL)-6 and tumor necrosis factor (TNF)-α, and causes LBW." (PMID 36294421, 2022). "Another cytokine showing a relationship with the presence of cancer cachexia and weight loss was TNF‐α." (PMID 35080147, 2022). "Serum levels of inflammatory markers like CRP, IL-6 and TNF are associated with the incidence of several cancers and mortality in cohorts and meta-analyses in the general population, with a modest effect size." (PMID 35406394, 2022). "Several functional single-nucleotide polymorphisms (SNPs) within the TNF-α gene were previously discovered and reported as cancer-related genetic alterations in a case-control research NCT04131478." (PMID 35159388, 2022). "TNFα is a critical pro-inflammatory cytokine implicated in the pathogenesis of various diseases such as cancer." (PMID 35050379, 2022). "Few studies focused on older persons, except a cohort study including 2400 American septuagenarians that found associations between higher CRP, IL-6 and TNF with all cancer incidence." (PMID 35406394, 2022). "Recent replication studies have demonstrated that TNF-α is associated with breast, ovarian, and oral cancers through the NF-κB pathway." (PMID 36139553, 2022). "In this context, inflammatory biomarkers, such as CRP, IL-6, IL-8, and TNFα, are associated with different types of cancer, such as breast and prostate." (PMID 35453382, 2022).
cancer (continued). "TNFR2 upregulation in colonic epithelial cells has also been reported in TNF-dependent cancer development associated with AOM/DSS-induced colitis." (PMID 35681583, 2022). "Namely, the association of ADIPOQ’s polymorphism rs266729 with TNF-α mRNA levels was recorded in the cancer group." (PMID 36429712, 2022). "Pro-inflammatory cytokine TNF-α was also implicated in cancer cachexia and shown to promote lipolysis in rodents and human adipocytes." (PMID 35646636, 2022). "Multivariable analysis found TNF inhibitor use to be consistently associated with a low risk of cancer development (adjusted HR, 0.492; 95% CI, 0.351–0.688 before matching; adjusted HR, 0.379; 95% CI, 0.255–0.563 after matching)." (PMID 35945635, 2022). "Lipopolysaccharide‐induced tumor necrosis factor-α factor enhances inflammation and is associated with cancer." (PMID 35512017, 2022). "Cancers are associated with the increased secretion of cytokines such as tumor necrosis factor (TNF) or IL-1, which causes local tissue damage; and subsequently, vegetation formation." (PMID 35573527, 2022). "Inflammatory cytokines including TNF-α, IL-6 and IL-8 play a major role in cancer-associated immune response." (PMID 36354990, 2022). "ADAM17 and TNFα are associated with chronic inflammatory conditions predisposing to cancer formation and metastasis." (PMID 36078095, 2022). "Although generally safe and effective, specific biologic classes such as tumor necrosis factor inhibitor (anti-TNF) medications are known to increase the risk of certain cancers." (PMID 35719803, 2022). "In parallel to these findings, other reports have emerged, connecting the presence of TNFα in tumors with pro-malignancy effects, and demonstrating that higher endogenous TNFα expression levels were associated with more advanced disease in cancer patients." (PMID 35663982, 2022). "TNF stimulates the survival and proliferation of malignant cells and has been associated with autophagy in cancer cells." (PMID 36559076, 2022). "TNF-α is one of the most important inflammatory mediators of the cancer-associated inflammatory networks." (PMID 36559076, 2022). "Many studies have reported that TNF mediates the inflammatory response, and continuous activation of TNF signaling has been implicated in the pathogenesis of cancer." (PMID 34995801, 2022). "Many patients with cancer cachexia suffer from inflammation associated with elevated cytokines, such as interleukin-1beta (IL-1β), interleukin-6 (IL-6), and tumor necrosis factor (TNF)." (PMID 36358681, 2022). "One of the most studied cytokines that has been linked to cancer is tumor necrosis factor α (TNF-α)." (PMID 35207722, 2022). "A meta-analysis in cancer survivors found that TNF-α and C-reactive protein levels decrease in association with combined aerobic and resistance training." (PMID 35328423, 2022). "It is worth to further investigate if cancer with loss of function or structural modification of IAP proteins would be eliminated at the insidious stage by a bacterial induction of TNFα in the body." (PMID 36119107, 2022). "GRb1 can ameliorate the symptoms of cancer cachexia by reducing TNF-α and IL-6 cytokine levels caused by inflammation in cancer cachectic mice." (PMID 36313365, 2022). "Previous reports indicate that IL-6, IL-8, or TNF-α are produced in excess in patients with IBD or cancer, and increased levels of these cytokines are associated with disease progression." (PMID 35739324, 2022). "The central mechanism behind cancer-associated cachexia is inflammation involving the overproduction of inflammatory cytokines, especially IL-6, TNF-α, and IL-1β." (PMID 36505042, 2022). "This nationwide cohort study assessed the risk of all-type and site-specific cancers in Korean patients with RA treated with TNF inhibitors and compared them to those treated with nbDMARDs, using a national administrative database." (PMID 35945635, 2022).
cancer (continued). "The activation of NF-κB by TNF-α and other pro-inflammatory cytokines are highly implicated in inflammation and cancer." (PMID 35265200, 2022). "M1-like macrophages secrete IL-12, TNF-α, reactive oxygen species (ROS) and so on, which are often resident in nomorxic region and associated with favorable prognosis in cancer patients." (PMID 35248069, 2022). "TNF-α was detected as an important factor in the cytokine system and a major intermediate for cancer-associated inflammation." (PMID 33517609, 2021). "Reports show that both cIAP1 and cIAP2 regulate TNFα-mediated NFƙB (Nuclear factor-kappa B) activation to execute apoptosis via TRAF2 (Tumor necrosis factor (TNF) receptor-associated factor-2) in cancer cells." (PMID 34712428, 2021). "They assessed the effects of TNF blockade and genotoxin colibactin-producing (clb+) E. coli in a model of colitis-associated cancer using DSS/Apcmin/+ mice and Apcmin/+; Il10−/− mice." (PMID 33578830, 2021). "Ten studies involving 26,509 patients with RA, PsA, or AS evaluated anti-TNFα drugs and reported a significant increase in cancer risk following treatment with anti-TNFα agents." (PMID 34790122, 2021). "As to cytokine release by CD8+ cells, we focused on TNF-α and IL-2, cytokines usually associated with cancer eradication." (PMID 34199263, 2021). "An increasing number of studies are showing that TNF-α and IL-6 are the primary inflammatory cytokines implicated in cancer cachexia, and these have emerged as critical factors related to the loss of muscle mass." (PMID 34724970, 2021). "CSG targeting of TNFα and IO-NP offers complementary therapeutic and diagnostic agents for fibrotic cancers that have aberrant laminin-nidogen-1 expression." (PMID 34683956, 2021). "Inflammatory pathways are linked to carcinogenesis and progression, and cancer patients often have elevated levels of pro-inflammatory cytokines (TNF-α, IL-6, and IL-1β) and expansion of regulatory cells (myeloid-derived suppressor cells and Tregs)." (PMID 34239993, 2021). "Approximately 28% of all cancers have been shown to be susceptible to direct induction of cell death by TNF-α." (PMID 33919653, 2021). "The main cause of FID in cancer is the release of cancer-associated pro-inflammatory cytokines such as interleukin (IL)-6, IL-1, TNF-α, and IFN-γ." (PMID 33777027, 2021). "Previous findings demonstrated that TNF-α had been implicated as a major factor in EMT through cancer initiation and progression in the TME." (PMID 33986746, 2021). "Inflammatory conditions can lead to increased expression of inflammatory cytokines, including interleukin-6, TNF, and IL-1β, which increase the risk of cancer." (PMID 34239566, 2021). "As expected, the TNF-based risk score was positively correlated with most steps of cancer-immunity cycles and immune cells in the TME in the Xiangya cohort." (PMID 35174161, 2021). "Few data are available regarding the association of TNF-α −1031T/C genotype variant with cancer-related cachexia or inflammation." (PMID 34900737, 2021). "In these experiments, cancer cells caused neutrophils to secrete large amounts of TNF-α and TGF-β in a co-culture model, indicating that the cytokines were responsible for regulating the EMT and the metastasis." (PMID 33986746, 2021). "In many human cancer tissues and in cancer induced by chemicals such as DEN, the development of cancer has been associated with an increase in macrophage cells and neutrophils, as well as an increase in the expression of TNF-α and its receptor TNFR-1." (PMID 35177980, 2021). "Translational repression of CYP3A genes, by the pro-inflammatory cytokine interleukin-6 (IL-6) and tumor necrosis factor α (TNF-α) have been suggested as the mechanisms causing decreased CYP3A-activity in cancer patients." (PMID 34572915, 2021). "Studies had proved that H. pylori infection promoted the expression of TNF-α and the development of cancers caused by H. pylori infection." (PMID 33865425, 2021).
cancer (continued). "At the molecular level, inflammation leads to the production of inflammatory cytokines, such as IL-6, IL-1β, and TNF, which have been associated with cardiovascular disease and several different types of cancer." (PMID 34234868, 2021). "The role of TNF-α, one of the important genetic variants of genes encoding pro-inflammatory cytokines, has been reported in cancer cachexia." (PMID 34900737, 2021). "In this study, cancer patients with higher concentration of TNF-α, IL-2R, IL-6, IL-8, and IL-10 had higher risk of death." (PMID 33735106, 2021). "Exposure to anti-TNFα agents was associated with an increased risk of cancer under the random-effects model (OR: 1.36, 95% CI: 1.20–1.53, p < 0.00001)." (PMID 34790122, 2021). "Several studies have suggested that NLR levels indicate cancer-associated inflammatory response, lymphocyte-mediated antitumor response, and production of cytokines, including tumor necrosis factor, interleukin-1, interleukin-6, and angiogenic factor VEGF." (PMID 34461485, 2021). "TNF via its receptors activates multiple signaling cascades leading to induction of inflammation, cell death, or cell survival and is implicated both in cancer development and progression." (PMID 33917839, 2021). "The cytokines TGF-β and TNF-α regulate apoptosis in various cancer cells and are associated with carcinogenesis." (PMID 33488300, 2021). "Gene ontology (GO), KEGG pathway enrichment and signaling network analyses revealed that the six SCCHN TMI genes are mostly associated with signaling networks involved in cancer-related transcriptional dysregulation and two important pathways: IL-17 and TNF." (PMID 34830910, 2021). "Accordingly, TNF-α-mediated NF-κB activation promotes wasting of muscle that leads to bodyweight loss ending with cancer cachexia." (PMID 34900737, 2021). "There is a study on inflammatory bowel disease in patients with a prior history of cancer showing that TNFα inhibition poses a mild risk of acquiring cancer." (PMID 33540543, 2021). "Thalidomide, an inhibitor of TNF-α synthesis with anti-inflammatory properties, attenuates weight loss in patients with cancer cachexia." (PMID 33801569, 2021). "Higher TNFα signaling in cancer cells was associated with higher activated Tm cell level and lower M2/higher M1 macrophage levels, while higher TGFβ signaling was associated with higher M0 macrophages level." (PMID 33767579, 2021). "Meanwhile, lymphocytes can release cytokines (such as IFN-β and TNF-α) that are associated with improved prognosis in several cancers." (PMID 34926234, 2021). "The variants demonstrated equal cell killing of B7H6low cancer cell lines but had higher interleukin (IL) 2 (IL-2), tumor necrosis factor-alpha (TNF-α), and IFN-γ secretion." (PMID 35011583, 2021). "The PRC2+-CGI genes that become silenced have been well-studied, but those that become activated have not, and appear to play important roles in pathways such as EMT and TNFα-associated inflammatory response in cancer." (PMID 33931649, 2021). "The different effect of anti-cancer drugs and TNF-α/SM treatment on FADD-deficient cells shows that the response of cells depends not only on the activity of signaling pathways but also on the drug used." (PMID 33800107, 2021). "Although the risk of anti-TNF-α-induced cancer for autoimmune patients is still debated, it provides a good example of a situation in which promoting tolerance via TNFR2 targeting would presumably be a better strategy than targeting TNF-α." (PMID 34712661, 2021). "There has been much discussion and controversy about the possibility of anti-TNF medications causing cancer." (PMID 34648530, 2021).